HIF1A (hypoxia inducible factor 1 subunit alpha)
Diseases named in the same sentence as HIF1A in open-access papers (continued):
Sharing a sentence is not in itself a finding about the gene and the disease.
cancer (continued). "For example, ET-1/ETAR may also promote cancer metastasis by regulating VEGF, matrix metalloproteinase, hypoxia-inducible factor-1alpha (HIF-1α), and the epithelial-to-mesenchymal transition." (PMID 23987636, 2013). "Both MYC and HIF-1α are direct targets of the RAS-BRAF-MEK-ERK pathway, suggesting an overall role of this pathway in the formation of various metabolic traits of cancer, including the “Warburg effect”." (PMID 23603840, 2013). "In this matter, we review recent findings indicating pivotal roles of HIF-1α and HIF-2α in the modulation of stemness properties and altered metabolic pathways of cancer stem/progenitor cells and their differentiated progenies during the development of diverse aggressive and recurrent cancers." (PMID 23301832, 2013). "We unveiled that, because of the insufficient delivery of glucose, most cancer cells in pimonidazole-positive regions are HIF-1α-negative in HeLa xenografts." (PMID 23203043, 2012). "It is also recognized that metastastic behaviour of cancer cells may be reinforced by hypoxia, a condition that induce up-regulation of CXCR4 expression mediated by hypoxia-inducible factor-1a (HIF-1α)." (PMID 22417013, 2012). "Knocking down HIF-1α, which leads to MMP-1 upregulation, might contribute to the degradation of the extracellular matrix of the peritoneum, allowing the invasion of cancer cells and the formation of peritoneal metastasis." (PMID 23181099, 2012). "Other group's data were already reported that absence of HIF-1α inhibited cell proliferation and induced apoptosis in cancer cells." (PMID 23243443, 2012). "As a result, the proportion of cancer cells in S-phase significantly increases in pimonidazole-positive/HIF-1α-negative layers (although a substantial number of cells seem to remain in G1/G0)." (PMID 23203043, 2012). "Here, we report a novel TG2-regulated pathway that constitutively activates NF-κB and increases the transcriptional regulation of the HIF-1α gene, thus linking these important pathways in a common mechanism induced by aberrant expression of TG2 in cancer cells." (PMID 23185316, 2012). "In contrast, the proliferative activity of cancer cells seems to be relatively attenuated in pimonidazole-positive/HIF-1α-negative layers." (PMID 23203043, 2012). "NOTCH1 correlated with the expression of various other cancer-related proteins like HIF1A but not with MUC1 as a marker of normal lung physiology." (PMID 23028920, 2012). "While HIF1α is expressed in all neoplastic cells and neural progenitors, HIF2α has a more specific function in cancer stem cells with no expression in normal progenitors." (PMID 22685459, 2012). "Differential mRNA and protein expression of HIF1α and HIF2α between nonstem and cancer stem cells have been demonstrated, although both factors have an essential role in promoting tumorigenesis." (PMID 22685459, 2012). "Several inhibitors targeting HIF-1α expression or its activities have been designed for the treatment of cancers; however, none of these compounds has yet been successful due to compound toxicity, limited activity, or poor pharmacological properties." (PMID 23028659, 2012). "The expression of COX-2 was positively correlated with the size of the cancer, lymphatic metastasis, surgical-pathologic and expression of HIF-1α (P < 0.05), but not with age, smoking and differentiated degree (P>0.05)." (PMID 21426663, 2011). "The expression of HIF-1α was positively correlated with the size of the cancer (P < 0.05), but not with age, smoking, lymphatic metastasis, differentiated degree and surgical-pathologic staging (P>0.05)." (PMID 21426663, 2011). "The expression of E-cadherin was positively correlated with differentiated degree and lymphatic metastasis (P < 0.05), but not with age, smoking, the size of the cancer, surgical-pathologic and expression of HIF-1α (P>0.05)." (PMID 21426663, 2011).
cancer (continued). "Future experiments may seek to test whether altered α-ketoglutarate or 2HG concentrations can affect HIF-1a or TET2 pathway members in vitro, and identify the cellular pathways necessary for the IDH mutants to exert a cancer-related phenotype." (PMID 21326614, 2011). "Furthermore, inhibition of PDK1 in cancer cells in vitro and in vivo results in a reduction of phosphorylated PDH and HIF-1α levels." (PMID 21541279, 2011). "Further, increased intracellular levels of Fe would increase the activity of prolyl hydroxylases potentiating hydroxylation of HIF-1α and HIF-2α, transcription factors that drive cancer growth, resulting in decreased HIF expression via ubiquination and proteasome digestion." (PMID 21453502, 2011). "Furthermore, cancer stem cells isolated from GBM and incubated under hypoxia show an overexpression of RAGE with a time course resembling that of HIF-1α." (PMID 21489226, 2011). "It was also recently reported that hypoxia induces the expression of TG2 via HIF-1α in some cancer cell types, but not in others." (PMID 21310073, 2011). "Since HIF-1α acts as a pro-angiogenic transcription factor and increases VEGF-A expression, we first thought that it was responsible for VEGF-A up-regulation in cancer cells exposed to amifostine in our experiments." (PMID 20334641, 2010). "The conclusion was drawn that HIF1α, not HIF2α, was responsible for the majority of the hypoxia response in cancer." (PMID 20104230, 2010). "Our data suggest that it may be advantageous to further develop compounds that are effective at inhibiting both HIF-1α and HIF-2α for cancer treatment." (PMID 21073737, 2010). "Taken together, these findings strongly indicate that 1, 9 PA can downregulate HIF-1α in human cancer cells through a mechanism(s) that is independent of the mechanism(s) by which it inhibits JNK." (PMID 21209911, 2010). "On multivariate analysis, HIF-1α positivity retained a significant effect on cancer-specific survival independent of TNM stage and vascular invasion (HR=4.11, 95% CI=1.37–12.35, P=0.012)." (PMID 19436307, 2009). "Given the apparent opposite effects of HIF-1α and HIF-2α on c-Myc, it is reasonable to ask (A) whether this phenomenon takes place in other cancer cells and (B) what is the mechanism?" (PMID 20046830, 2009). "Using immunofluorescence microscopy, we observed different patterns of subcellular localization of HIF-1α/FLuc fusion protein between normal cells and cancer cells; similar differences were observed for HIF-1α in non-transduced, wild-type cells." (PMID 19347037, 2009). "Although hypoxia is one of the most potent stimulators of VEGF, interestingly, not all of the in situ and invasive cancers expressed HIF-1α." (PMID 19623180, 2009). "In several types of cancer, hypoxia-induced HIF-1α expression seems to be characterized by a peri-necrotic distribution, whereas oxygen-independent overexpression results in a diffuse pattern of HIF-1α immunoreactivity." (PMID 16168127, 2005). "As a result, variations in HIF-1α activity rather than expression alone may contribute to its differing prognostic significance across cancer types." (PMID 41526224, 2026). "Moreover, HIF-2α mRNA lacks miRNA sequences targeting it for degradation, unlike HIF-1α mRNA targeted by tissue-specific miRNAs in various cancers." (PMID 39470609, 2025). "Moreover, the increased glycolytic activity under hypoxia promotes survival pathways, such as HIF-1α and AMPK, enhancing resistance to therapies; consequently, cancer cells can survive and resist the apoptotic signals that typically arise from ROS accumulation during treatment." (PMID 39857427, 2025). "Under hypoxic conditions, HIF1α is stabilized and activated, leading to the upregulation of key factors, including vascular endothelial growth factor (VEGF), which drives angiogenesis, matrix metallopeptidase 9 (MMP9), and MMP7, which enhance cancer invasion, and EMT-related genes." (PMID 39996805, 2025).
cancer (continued). "Compounds that disrupt HIF signaling pathways, including HIF-1α inhibitors and prolyl hydroxylase inhibitors, have demonstrated potential in preclinical research by effectively suppressing HIF-mediated autophagy and improving the effectiveness of standard cancer treatments." (PMID 40004215, 2025). "HIF-1α and HIF-2α share highly conserved domains, engage in similar protein–protein interactions (PPI) for activation, and bind to the same HRE binding site, they display differences in gene expression patterns, tissue distributions, and implications in cancer." (PMID 39470609, 2025). "Additionally, HIF-1α induces the expression of genes involved in glucose metabolism, such as GLUT-1 and glycolytic enzymes, promoting the Warburg effect – an altered metabolic pathway that enables cancer cells to thrive in hypoxic conditions." (PMID 40901111, 2025). "UBE2S, HIF‐1α, and FOXM1 may play a role in the progression of esophageal HIN and LIN to cancer." (PMID 41427004, 2025). "Moreover, STAT3, but not HIF-1α, plays an important role in hypoxia-induced chemoresistance in BC cancer." (PMID 38415469, 2025). "This review explores the molecular mechanisms of action of HIF-1α in IVM, its impact on immunotherapy resistance, as well as potential interventions, emphasizing the need for innovative approaches to circumvent hypoxia-driven immunosuppression in cancer therapy." (PMID 39981236, 2025). "In breast cancer, Hif-1α no longer performs its canonical role as a transcription factor under hypoxic conditions, but instead interacts directly with γ-secretase regulates its activity for Notch cleavage, and enhances cancer cell migration and metastasis." (PMID 40927393, 2025). "Interestingly, low expression of DUSP2 and high expression of HIF-1α were associated with poor prognosis in ER-negative BC patients, further supporting the relevance of a HIF1α/DUSP2/ERK axis in cancer." (PMID 40943262, 2025). "HIF1α, which transcriptionally induces vascular endothelial growth factor (VEGF) to promote angiogenesis, upregulates glucose transporter 1 (GLUT1), and upregulates glycolytic and pentose phosphate pathway (PPP) enzymes, is currently considered as a central driver of cancer metabolic reprogramming." (PMID 41020695, 2025). "In addition, HIF-1α regulates the expression of nitric oxide synthase and insulin-like growth factor 2 (IGF2), which plays a key role in the proliferation and survival of cancer cells." (PMID 41515435, 2025). "The results indicated that regions with high HIF1A expression were correlated with an increased accumulation of SPP1+CD68+TAMs and HIF1A+ɑSMA+CAFs, suggesting the role of hypoxia in promoting the formation of the aggressive multicellular community and thus accelerating cancer progression in TNBC." (PMID 40432877, 2025). "However, only the AC1 cluster expressed a high level of HIF-1α transcriptome, and this feature was remarkably reduced in ASH1L-depleted tumors, strengthening the crucial role of ASH1L in regulating HIF-1α transcriptome in invading cancer cells." (PMID 40394007, 2025). "Therefore, HIF-1α expression has been observed in primary and metastatic breast cancer but not in normal tissue around the cancer." (PMID 40430040, 2025). "HIF-1α plays a role in therapy resistance via various mechanisms, notably by activating multidrug resistance (MDR) proteins, such as P-glycoprotein (P-gp) and breast cancer resistance protein (BCRP), which facilitate the efflux of chemotherapeutic agents from cancer cells." (PMID 40136686, 2025). "Hypoxia-inducible factor-1 alpha (HIF-1α) is a transcription factor that is normally deactivated in an oxygen-rich environment but activated in an oxygen-poor environment and upregulated gene expression related to cancer progression, such as angiogenesis and metabolism reprogramming." (PMID 40699805, 2025). "Notably, RUNX2 enhances HIF-1α-mediated VEGF induction, and recent studies suggest that RUNX2 may also contribute to drug resistance in malignant tumours." (PMID 40806771, 2025).
cancer (continued). "The observed significant suppression of STAT3 and HIF-1α mRNA levels in F9 cancer cells (absent in fibroblasts) correlates with the anti-cancer effects of exogenous SELENOV and may represent an important aspect of its therapeutic potential." (PMID 41463386, 2025). "The Cancer Genome Atlas (TCGA), Cancer Cell Line Encyclopedia (CCLE), and Sequence-based RNA Adenosine Methylation Site Predictor (SRAMP) databases were used to evaluate the expression of OTUD7B in ESCC and its correlation with methyltransferase-like 14 (METTL14) and HIF-1α." (PMID 40746896, 2025). "Constitutive HIF1A is detectable in non-hypoxic cancer cell lines in response to lactate and pyruvate as evidenced by the accumulation of HIF1A protein in many cancer cell lines due primarily to lactate that prevents degradation of HIF1A." (PMID 39529665, 2024). "The effect of E6 and E7 may be the non-hydroxylation and non-ubiquitination of HIF-1α, which may regulate metabolic processes involved in metabolic reprogramming in cancer upon stabilization, non-degradation, and translocation to the nucleus." (PMID 38921041, 2024). "Notably, HIF1α activates the expression of genes such as MDR1/P-glycoprotein (P-gp), a key efflux pump involved in multidrug resistance, which expels chemotherapeutic drugs from cancer cells, reducing their intracellular levels and effectiveness." (PMID 39697237, 2024). "This suggested that the inhibition of SP1, MYC, and HIF1A should have strong negative impacts on the expression of stem cell- or EM transition-related cellular mechanisms that play important roles in the progression of cancer cells." (PMID 39590335, 2024). "The combined expression of PLGF, HIF-1α, VEGFR1 (FLT1 gene), and PD1 was associated with several cancer hallmarks, regardless of cancer type, including tissue invasion and metastasis, sustained angiogenesis, persistent proliferative signaling, immune evasion, and reprogramming of energy metabolism." (PMID 39457506, 2024). "HIF1α activity downregulates the expression of carnitine palmitoyltransferase 1A (CPT1A) and medium- and long-chain acyl-CoA dehydrogenases, key enzymes for the import of mitochondrial fatty acids and for the β-oxidation of lipids, thus limiting fatty acid catabolism in cancer cells." (PMID 39284708, 2024). "NRF2-inhibited cancer cells failed to accumulate HIF-1α protein in hypoxic conditions, likely due to reduced mitochondrial O2 consumption that enables PHD hydroxylation of HIF-1α and consequent protein degradation: this mechanism limits the expression of VEGF and other HIF-1 target genes." (PMID 39062921, 2024). "Given that our study focuses mainly on HIF-1A as a candidate prognostic marker for HCC, we specifically chose pathways that include HIF-1A, particularly the pathways involved in metabolic reprogramming, as it is one of the main cancer-related properties affected by HIF-1A." (PMID 39567394, 2024). "It is worth noting that the relationship pattern between EZH2 and HIF‐1α is not unique in cancer." (PMID 38072662, 2024). "The present data on ACE2 siRNA transfection demonstrated the downregulation by ACE2 of HIF1α, MMP9 and β catenin in A549 cells, suggesting that the interaction between ACE2 and HIF1α and other cancer-promoting genes could differ depending on the cancer type." (PMID 39273283, 2024). "Despite the recognition of HIF-1α as a crucial regulator of ESCC, the precise molecular mechanisms governing its regulation in cancer cells remain unclear, and the potential for targeting the ubiquitin degradation of HIF-1α in clinical contexts requires further exploration." (PMID 38402183, 2024). "By targeting SMURF2 to modulate HIF1α stability, it may be possible to influence hypoxia-related cancer pathways without directly inhibiting HIF1α itself, presenting a novel therapeutic approach." (PMID 39697237, 2024).
cancer (continued). "In addition, our identification of HIF1A upregulation during the EMT process (VIM 4–5) indicates that HIF1A upregulation is intrinsic to carcinoma cells undergoing EMT rather than being induced by a hypoxic microenvironment." (PMID 39256881, 2024). "As HIF1α a key transcription factor involved in the adaptation of normal and cancer cells to hypoxia, we investigated the hypothesis that hypoxic PD-L1 regulation is HIF dependent." (PMID 37067635, 2023). "Moreover, increased intracellular iron sequestration may promote hypoxia inducible factor-1α (HIF-1α) degradation via prolyl hydroxylation, thereby reducing EPO production in patients with cancer." (PMID 37208766, 2023). "Furthermore, Kaempferol showed anti-cancer potential via numerous pathways including the inhibition of angiogenesis as well as the expression of VEGF, regulation of hypoxia-inducible factor 1-alpha (HIF-1α) apoptosis induction, induction of G2/M cell cycle arrest and caspase-3-dependent apoptosis." (PMID 37239974, 2023). "Under hypoxia, HIF1α directly inhibits miR-338-3p transcription, leading to increased expression of its downstream target and EMT-related transcription factor, ZEB2, which then promotes cancer progression, EMT, and metastasis in an NF-kB and PI3K/Akt signaling-dependent manner." (PMID 37583933, 2023). "Notably, in several types of cancer, including ER + breast malignancy, various oncogenic signalling mechanisms have been shown to activate HIF-1α-related pathways independent of hypoxic stimulation." (PMID 37166494, 2023). "In addition, many studies have shown that SP1, HIF1A, and MYC are often upregulated in cancer." (PMID 37998757, 2023). "There is potential in using these agents to treat AR-V7 expressing CRPC, however due to the conflicting reports in literature often stating HIF1α upregulation in many cancers, this may not be the ideal strategy for treatment." (PMID 36937454, 2023). "Despite HIF-1α and HIF-2α sharing similar abilities to dimerize with HIF-β, bind to genes whose promoters containing the HRE motif, and activate downstream expression of hypoxia-inducible genes, they differ in expression levels during different timings in cancer progression." (PMID 37460927, 2023). "Since PKM2 has also been reported to promote HIF-1α-mediated activation of glucose metabolism-related genes, including GLUT1, in cancer cells, it was rational to hypothesize that PKM2 might play a pivotal role in the acquired resistance to erlotinib and aggressive phenotype of OSCC." (PMID 36611972, 2023). "It has been reported that MT4-MMP expression is induced by hypoxia through the hypoxia-inducible factor-1-α (HIF1-α) and the activation of SLUG, a known transcription factor involved in epithelial–mesenchymal transition (EMT) which promotes the malignant capacity of cancer cells." (PMID 37373092, 2023). "Moreover, by inhibiting the release of exosomes containing GRP78 from cancer cells, HDAC6 inhibition also inhibits angiogenesis as GRP78 is involved in blood vessel formation in growing tumors through the activation of HIF-1α and VEGF/VEGFR, as well as the PI3K/AKT, ERK, and FAK signaling pathways." (PMID 38258065, 2023). "Targeting the hypoxic conditions and HIF1α function in combination with anti-PD-L1 immunotherapy can overpass the adverse effect PD-L1, whether attributed to HIF1α or IFNγ in the TME, by enhancing the recognition of cancer cells and allowing effective cancer cell killing by the immune system." (PMID 37067635, 2023). "However, there are other pathways independent of HIF-1α that enable cancer cell proliferation and survival under hypoxic conditions." (PMID 37233716, 2023). "By fusing an oxygen-sensitive subdomain of HIF1α to a CAR scaffold, CAR-T cells that are locally responsive to a hypoxic environment can be generated, which could be a promising therapeutic approach for restoring T cell function during cancer." (PMID 37342333, 2023).